PSMA2P1 (proteasome subunit alpha 2 pseudogene 1)
Gene: Processed pseudogene on chromosome 11 (87,329,407 to 87,330,052, reverse strand). Ensembl gene ENSG00000254582.
Diseases named in the same sentence as PSMA2P1 in open-access papers:
PSMA2P1 is named in the same sentence as 1 disease in open-access papers, as found by Europe PMC text mining. Sharing a sentence is not in itself a finding about the gene and the disease. The quoted sentences say what the papers report.
cognitive decline (1 paper, 2025). "PSMA2P1 and RNU6-1135P exhibited high expression in the artery and adipose tissues; however, their roles in cognitive decline, warrant further investigation." (PMID 40728933, 2025).